ANO7 (anoctamin 7)
Description:
Has calcium-dependent phospholipid scramblase activity; scrambles phosphatidylserine, phosphatidylcholine and galactosylceramide (By similarity). Does not exhibit calcium-activated chloride channel (CaCC) activity. May play a role in cell-cell interactions.
Synonyms: D-TMPP; NGEP; PCANAP5; TMEM16G; PCANAP5L; IPCA-5; DTMPP; IPCA5
Tractability: Antibody: UniProt places it where antibodies can reach, with high confidence; its Gene Ontology location is reachable by antibodies, with high confidence; UniProt predicts a signal peptide or a membrane-spanning region.
Gene: Protein-coding gene on chromosome 2 (241,188,509 to 241,225,993, forward strand). Ensembl gene ENSG00000146205.
Subcellular location: Cell membrane (Isoform 1); Cell junction; Endoplasmic reticulum; Cytoplasm, cytosol (Isoform 2)
Pathways (Reactome):
Disease: Induction of Cell-Cell Fusion
Transport of small molecules: Stimuli-sensing channels
Gene Ontology:
Molecular function: intracellularly calcium-gated chloride channel activity; chloride channel activity; phospholipid scramblase activity; protein dimerization activity
Biological process: chloride transmembrane transport; calcium activated phospholipid scrambling; monoatomic ion transmembrane transport
Cellular component: anchoring junction; endoplasmic reticulum; plasma membrane; cytosol
Genetic constraint (gnomAD): Loss-of-function variants: 103 observed, 104.64 expected, observed/expected ratio (o/e) 0.98, 90% interval 0.84 to 1.16. The upper end of that interval is the gene's LOEUF score, 1.16, which puts it in group 5 of 6, group 1 being the genes least tolerant of losing a copy. Missense variants: 1,162 observed, 1,051.2 expected, observed/expected ratio (o/e) 1.11, 90% interval 1.05 to 1.16. Synonymous variants: 499 observed, 433.86 expected, observed/expected ratio (o/e) 1.15, 90% interval 1.07 to 1.24.
Homologues: Orthologues: chimpanzee ANO7 (99% identical), macaque ANO7 (95% identical), mouse Ano7 (82% identical), rat Ano7 (81% identical), dog ANO7 (76% identical), zebrafish ano7 (57% identical). Paralogues in human: ANO1 (37% identical), ANO4 (37% identical), ANO3 (37% identical), ANO2 (36% identical), ANO5 (35% identical), ANO6 (35% identical), ANO9 (29% identical), ANO8 (21% identical), ANO10 (21% identical), PPP1R7 (9% identical).